KIAA2012 (KIAA2012)
Gene: Protein-coding gene on chromosome 2 (202,073,255 to 202,205,188, forward strand). Ensembl gene ENSG00000182329.
Genetic constraint (gnomAD): Loss-of-function variants: 110 observed, 139.09 expected, observed/expected ratio (o/e) 0.79, 90% interval 0.68 to 0.93. The upper end of that interval is the gene's LOEUF score, 0.93, which puts it in group 3 of 6, group 1 being the genes least tolerant of losing a copy. Missense variants: 1,174 observed, 1,353.2 expected, observed/expected ratio (o/e) 0.87, 90% interval 0.83 to 0.91. Synonymous variants: 451 observed, 507.44 expected, observed/expected ratio (o/e) 0.89, 90% interval 0.82 to 0.96.
Homologues: Orthologues: chimpanzee KIAA2012 (98% identical), macaque KIAA2012 (91% identical), dog KIAA2012 (74% identical), pig KIAA2012 (74% identical), rabbit KIAA2012 (64% identical), rat Kiaa2012 (62% identical), mouse Gm973 (54% identical), tropical clawed frog kiaa2012 (33% identical).
Diseases named in the same sentence as KIAA2012 in open-access papers:
KIAA2012 is named in the same sentence as 1 disease in open-access papers, as found by Europe PMC text mining. Sharing a sentence is not in itself a finding about the gene and the disease.
KIAA2012 shares sentences with these, for which no sentence is quoted: meningioma (1 paper).